RIPK1 (receptor interacting serine/threonine kinase 1)
Diseases named in the same sentence as RIPK1 in open-access papers (continued):
Sharing a sentence is not in itself a finding about the gene and the disease.
cancer (173 papers, 2014 to 2026). A tumor composed of atypical neoplastic, often pleomorphic cells that invade other tissues. "Following RIPK1 degradation and loss of scaffold function, cancer cells become more sensitive to therapy-induced TNF and interferon, thereby enhancing the immunostimulatory effects of radiotherapy and immunotherapy." (PMID 41334873, 2025). "Various diseases, such as autoimmune disorders, inflammatory diseases, neurodegenerative conditions, and certain cancers, have been linked to RIPK1-mediated pathways, drawing the attention of various researchers." (PMID 40565018, 2025). "To further validate the structural model we conducted literature and database mining to identify known mutations in RIPK1 DD associated with the cancer." (PMID 40240880, 2025). "Overall mapping of RIPK1 DD mutations in cancer further supports our structural model and the role of type-II interactions of RIPK1 DD in the necrosome assembly." (PMID 40240880, 2025). "The association between genetic variation of RIPK1 gene and disease including cancers has been reported." (PMID 37996860, 2023). "In this regard, it is likely that s CYLD mutation or deficiency in some cancers decreases its deubiquitination activity against K63-linked or M1-linked Ub chains, leading to insufficient activation of RIPK1-mediated cell death." (PMID 36171264, 2022). "Apoptotic/necrotic death induced by Smac mimetics and TNF-α crucially depends on RIPK1 because RIPK1 deficient MEFs, and cancer cells in which RIPK1 is depleted, are resistant to TNFR1 killing following treatment with Smac mimetics." (PMID 35406442, 2022). "Over the years, interest in the correlation between gene mutations associated with RIPK1 and cancer has grown." (PMID 33567618, 2021). "Our results add more roles of RIPK1 in cancer, we showed that loss of RIPK1 expression enhanced Poly(I:C)-induced invasion in CCA cells." (PMID 33036630, 2020). "In contrast to this, higher expression of RIPK1 was also linked to a worse prognosis and higher metastasis rate in melanoma, potentially due to NF-κB-dependent stimulation of cancer cell proliferation." (PMID 32752206, 2020). "It has been reported that RIPK1 is implicated in some diseases, such as chronic periodontitis, liver diseases, and cancers." (PMID 32272907, 2020). "Product of cholesterol metabolism such as 24(S)-hydroxycholesterol and 4-cholesten-3-one were found to be associated with RIPK-1 activation in neurons and ROS mediated induction of autophagy in cancer cells." (PMID 29467593, 2018). "Therefore, chemotherapy-induced cancer cell death is also dependent on the kinase function of RIPK1, and the loss of RIPK1 function is likely to lead to increased drug resistance in cancer cells." (PMID 41334873, 2025). "RIPK1 is implicated in a broad range of human diseases, and there is significant interest in development of therapeutics to target RIPK1 kinase activity in a variety of human inflammatory diseases, neurodegenerative conditions, and cancer metastasis." (PMID 39186805, 2024). "However, studies associated with cancer show that RIPK1 is a gene with “two faces” in both pro- and anticarcinogenic functions." (PMID 36050939, 2022). "Thus, under these experimental conditions, both monovalent and bivalent IAP antagonist treatment resulted in sufficient cIAP1 loss to support RIPK1:caspase-8 complex formation and induction of apoptosis in sensitive cancer cell lines." (PMID 28149532, 2017). "Our results suggested that RIPK1 is associated with activation of the extrinsic cell death pathway in PCTAIRE1 knockdown cancer cells, which supports findings in several reports indicating that modulation of RIPK1 expression is associated with the extrinsic apoptotic pathway." (PMID 25790448, 2015).
cancer (continued). "Moreover, membrane depolarization is a crucial event in the activation of TRAIL, a ligand that causes fragmentation of mitochondria in multiple human cancer cell lines, ultimately inducing apoptosis and necroptosis by activating caspases and RIPK1/RIPK3, respectively." (PMID 37612409, 2023). "Therefore, elucidation of the mechanisms by which RNF4 promotes RIPK1-mediated cell death may open up possibilities for new therapeutic strategies for cancers associated with overexpression of RNF4." (PMID 34071450, 2021). "It was observed that the degradation of RIPK1 enhanced the immunostimulatory effects of radio- and immunotherapy by sensitizing cancer cells to treatment-induced TNF and interferons in several malignant cell lines." (PMID 40565018, 2025). "In its inactive state, RIPK1 functions as a scaffold protein that protects cancer cells from immunodetection and death effects." (PMID 41334873, 2025). "Conversely, in other cancers, like head and neck tumors, RIPK1 expression appears subdued, yet this downregulation still seems to encourage tumor progression." (PMID 40007541, 2025). "Upstream sensors like ZBP1, AIM2, and RIPK1, along with regulators identified in cancer-related PANoptosis studies, such as IRF1, ADAR, MAP3K7, and NFS1, were also incorporated for their significant regulatory roles." (PMID 39901195, 2025). "The role of RIPK1 and necroptosis in carcinogenesis, as well as its effect on course of disease and prognosis, has been shown in many cancers." (PMID 40508046, 2025). "For instance, RIPK1 depletion has been observed in the cancer tissue of patients with triple-negative breast cancer (TNBC) compared to normal breast tissue, and this downregulation is highly associated with improved patient survival." (PMID 41334873, 2025). "Genetic interaction screening demonstrated RIPK1 regulates the TNF signalling pathway via NF-κB in cancer cells and plays a critical role in modulating cell death." (PMID 41334873, 2025). "As a central regulator of cell death, RIPK1’s role in cancer progression remains context-dependent, with its dual functionality offering both pro-tumorigenic and anti-tumorigenic effects." (PMID 41334873, 2025). "Quantitative mass spectrometry analysis in combination with functional genomics data revealed lower numbers of RIPK3 compared to RIPK1 in the majority of cancer cells." (PMID 40240880, 2025). "Knockout of RIPK1 expression in cancer cells impaired chemokine secretion, reduced the recruitment of ARG1+ inhibitory myeloid cells, and was associated with the failure of ICB therapy in mice." (PMID 41334873, 2025). "The scaffolding function of RIPK1 contributes to both intrinsic and extrinsic resistance to immune checkpoint blockades (ICBs), making it a compelling therapeutic target for cancer treatment." (PMID 40665578, 2025). "Data from the Human Protein Atlas (HPA) and The Cancer Genome Atlas (TCGA) indicate that RIPK1 is expressed across a spectrum of cancers." (PMID 40007541, 2025). "In the regulation of sensitivity of cancer cells to T cell-mediated killing, positive selection was found in DNA Binding transcription factor activity, IFNγ signaling, necroptosis, RIPK1-mediated necrosis, and the TNF pathway." (PMID 39868264, 2025). "Our model was extensively validated by mapping the amino acid substitutions of RIPK1 DD observed in cancer tissue samples." (PMID 40240880, 2025). "To date, studies on various types of cancer have demonstrated distinct levels of RIPK1 expression in cancer cells or tissues." (PMID 41334873, 2025). "Numerous studies have extensively explored diseases related to RIPK1 expression, encompassing liver injuries, skin diseases, cancers, and more." (PMID 40007541, 2025). "In line with that, MOC1 carcinoma cells were highly susceptible to necroptosis with rapid cell death induction on exposure to TSZ, which was completely blocked by the necroptosis/RIPK1 inhibitor necrostatin-1." (PMID 40345706, 2025).
cancer (continued). "While cancer cells with high levels of caspase-8 underwent apoptosis, caspase-8 depletion downregulated NF-κB signaling, increased RIPK1 stability, and facilitated necroptotic cell death." (PMID 38877579, 2024). "Clinical studies have implicated human RIPK1 in a wide range of systemic disorders and pathologies, leading to substantial interest in developing RIPK1 therapeutics, particularly for treating inflammatory diseases and cancer." (PMID 39186805, 2024). "Definitive evidence has shown that inducing RIPK1/ RIPK3-mediated necroptosis has the ability to eliminate cancer cells that have acquired resistance to apoptosis." (PMID 38553639, 2024). "The scaffolding function of receptor interacting protein kinase 1 (RIPK1) confers intrinsic and extrinsic resistance to immune checkpoint blockades (ICBs) and has emerged as a promising target for improving cancer immunotherapies." (PMID 38659866, 2024). "Comparative analyses of human CRC tissues and adjacent normal tissues showed significantly elevated expression of RIPK1 levels in the cancerous tissues, correlating positively with the cancer progression stages and three-year mortality rates." (PMID 39540935, 2024). "HOIP participates in NF-κB signaling, cell death, inflammation, immunity, and cancer by conjugating linear ubiquitin chains onto a few proteins, such as RIPK1, RIPK2 and NEMO4–7." (PMID 38582895, 2024). "In this regard, it was reported that drug activation of receptor-interacting serine/threonine-protein kinase 1 (RIPK1) can trigger cell death that evokes the immune system response against cancer." (PMID 38891056, 2024). "Considering the predicted safety profile of RIPK1 degradation based on human genetics, we envision that further optimized RIPK1 degraders have the potential to improve cancer immunotherapy." (PMID 39681571, 2024). "Nanomedicines can initiate a cascade leading to the rupture of cancer cell membranes and subsequent cell death by targeting specific receptors or signaling proteins involved in necroptosis, such as RIPK1 or RIPK3." (PMID 39209834, 2024). "LD4172 induces potent and specific RIPK1 degradation and sensitizes multiple preclinical cancer models to anti-PD1 therapy." (PMID 39681571, 2024). "The scaffolding function of receptor interacting protein kinase 1 (RIPK1) confers intrinsic and extrinsic resistance to immune checkpoint blockades (ICBs) and emerges as a promising target for improving cancer immunotherapies." (PMID 39681571, 2024). "In the case of cancers, plenty of studies have recently demonstrated that RIPK1 plays a critical role in cancer immune checkpoint blockade (ICB) by modulating inflammation or immunity-related signaling pathway." (PMID 37462822, 2023). "In cancer cell lines that ubiquitously express RIPK1, the availability of RIPK3 correlates with their sensitivity to necroptosis induction." (PMID 36774342, 2023). "RIPK1 is highly expressed in KIRC and is upregulated by TNF-α, which further induces necrotic apoptosis of cancer cells through the RIPK1/RIPK3/MLKL/Drp1 axis." (PMID 37847185, 2023). "RIPK1 has been implicated in TNF-induced cell death and proposed as a target for cancer therapy to induce cancer cell death." (PMID 37090690, 2023). "Ultimately, it leads to the degradation of RIPK1 protein, down-regulates the downstream necroptosis pathway proteins, and promotes cancer cell progression by inhibiting necroptosis." (PMID 36604411, 2023). "For instance, FADD, FASLG, RIPK1, RIPK3, and TNF were more prone to copy number gain than loss in pan-cancer, but FAS and TLR3 displayed the reverse tendency." (PMID 37351504, 2023). "The activation of mitophagy in cancer during the detachment from ECM depends on the expression of receptor-interacting protein kinase 1 (RIPK-1), and secretion of ECM protein decorin." (PMID 36906534, 2023).
cancer (continued). "The identification of 5-ITu – an FDA-approved compound and genotoxic drug with anti-cancer potential—as modulator of RIPK1-dependent death, in combination with p38/MK2 inhibitors and SM opens possibilities for future therapies." (PMID 37495567, 2023). "Pazopanib is an FDA-approved anti-cancer drug that is reported to be a potent necroptosis inhibitor via RIPK1 inhibition." (PMID 37458952, 2023). "IFN-γ-treated cancer cells also upregulate RIPK1, which connects TNF signalling to NF-κB that in turn induces an immunosuppressive chemokine program." (PMID 37503572, 2023). "An FDA-approved anti-cancer drug, pazopanib, is reported to possess potent inhibitory effect against necroptosis via interfering with RIPK1." (PMID 37458952, 2023). "PK68 is a potent and selective inhibitor of RIPK1 and also highlights its great potential for use in the treatment of cancer metastasis." (PMID 37865804, 2023). "In comparison, FADD in 12 cancer types, FASLG in 3 cancer types, RIPK1 in 19 cancer types, TLR3 in 25 cancer types, TNF in 11 cancer types, FAS in 22 cancer types, MLKL in 15 cancer types, and RIPK3 in 12 cancer types had homozygous deletions." (PMID 35748782, 2022). "Shikonin was reported to exert anti-cancer effects by mediating RIPK1 and RIPK3 expression to induce necroptosis in pancreatic cancer and osteosarcoma." (PMID 35479956, 2022). "Among them, MLKL was highly expressed in cancer tissues, while RIPK1 and RIPK3 were lowly expressed in cancer tissues." (PMID 36544770, 2022). "The interaction of stem cell factor SOX9 with RIPK1 in the cytoplasm would contribute to the suppression of cancer cell death and stemness in metastatic ovarian cancer." (PMID 35159173, 2022). "In summary, our results demonstrated that IDOAMP inhibited Aurora kinase A, promoting the RIPK1/RIPK3/MLKL necrosome activation to antiprostate cancer." (PMID 35965682, 2022). "Depending on the microenvironment of cancer cells, complex I activates downstream signaling pathways by regulating RIPK1, which can lead to apoptosis and necroptosis." (PMID 36204681, 2022). "Beyond apoptosis, other different types of cell death have been described after AdipoRon administration in cancer models, however, including RIPK1/ERK-dependent necroptosis and AMPK-mediated autophagy." (PMID 34070338, 2021). "Under physiological conditions, RIPK1 synergizes with NF-ĸB to prevent hepatocyte apoptosis, chronic liver disease and cancer." (PMID 33567618, 2021). "These strategies enabled to study RIPK1 behavior in the contexts of cell survival and cell death, helping the study and the treatment of several diseases including cancers." (PMID 33567618, 2021). "The role of RIPK1 is widely discussed in inflammatory pathologies and diseases but little is known about its biological relevance in cancer." (PMID 33567618, 2021). "Receptor-interacting protein kinase 1 (RIPK1) polyubiquitination by IAPs has been shown to promote cytoprotection and cell survival in cancer cells via NF-κB activation." (PMID 34025452, 2021). "The expression of HSP90α, HIF1α and RIPK1 was stronger in cancer tissues than in liver tissues; however, RIPK3 was expressed more in liver tissues." (PMID 33440739, 2021). "One recent study demonstrated that sirtuins are able to control RIPK1-caspase 8-induced apoptosis in cancer." (PMID 33282964, 2020). "While the term “immunogenic cell death” is not fully defined, activation of receptor‐interacting serine/threonine‐protein kinase 1 (RIPK1) can induce a type of death that mobilises the immune system against cancer." (PMID 32419365, 2020). "More importantly, this is the first study to demonstrate the dual roles of RIPK1 representing a key mediator in this treatment strategy by regulating both cell death and invasion of cancer cells." (PMID 33036630, 2020). "The potential roles of RIPK1 in cell death regulation has been extensively reported but its roles in cancers have virtually remained debatable." (PMID 33036630, 2020).
cancer (continued). "Together, our study demonstrates that PK68 is a potent and selective inhibitor of RIPK1 and also highlights its great potential for use in the treatment of inflammatory disorders and cancer metastasis." (PMID 31235688, 2019). "Many cancer cell lines, however, express RIPK1 in attached and detached conditions and possibly develop a capacity to restrict RIPK1-mediated cell death." (PMID 31447323, 2019). "We have described the use of a potent small molecule inhibitor of RIPK1 named GSK’963 for the improvement of the therapeutic window of an antibody-TNF fusion protein (L19-TNF) in preclinical models of cancer." (PMID 31803362, 2019). "Quantitative RT-PCR demonstrated that RIPK1 was expressed equally in both cancer cell lines at the mRNA and protein levels." (PMID 25888634, 2015). "However, some studies indicate that RIPK1 levels are significantly reduced in several certain cancers." (PMID 41334873, 2025). "Finally, the role of the balance between RIPK1 and RIPK3 in inducing cell death in cancer cells has recently been highlighted by the study using Protac targeting RIPK1, which was able to induce cell death in cancer cells." (PMID 40240880, 2025). "Correlation analysis showed that SPOP and RIPK1 were positively correlated in all 5 cancer types." (PMID 41122967, 2025). "As an important target of cell necroptosis, RIPK1 is also an important pathway for some nanomaterials such as N-TiO2 and SeNPs to induce cell necroptosis, which is an important direction in the research of nanomaterials in the treatment of cancer." (PMID 40301325, 2025). "In accordance with these observations, the analysis of the mRNA expression levels of RIPK1 and RIPK3 using The Cancer Genome Atlas (TCGA) database revealed that the mRNA of RIPK1 has significantly higher expression levels than the one of RIPK3 in most cancer tissues (Fig. EV3G)." (PMID 40240880, 2025). "Future research should further explore RIPK1 within specific cancer contexts, such as RCC." (PMID 41334873, 2025). "Moreover, recent evidence also suggests that cancer cells hijack RIPK1 (i.e., stabilise its scaffold function) to enhance cell survival, induce TNF insensitivity, and confer resistance to immunotherapy." (PMID 41334873, 2025). "Furthermore, we enumerate several identified RIPK1-targeted inhibitors with potential for cancer therapy." (PMID 41334873, 2025). "Interestingly, Nec‐1 did not rescue radiation‐induced cell death in H295R cells; further analysis of RIPK1 expression in the cancer cell lines showed that TPC‐1, 8505‐C, and SW13 cells expressed RIPK1, whereas H295R cells did not." (PMID 39425547, 2025). "This suggests that RIPK1 polyubiquitin regulation could provide an excellent target for cancer therapy." (PMID 40169858, 2025). "Given that SPOP upregulates RIPK1 protein levels, rendering cancer cells more prone to apoptosis, RIPK1 could be an effective target for tumors with overexpressed SPOP like RCC." (PMID 41122967, 2025). "The majority of research indicates that RIPK1 overexpression contributes to cancer progression." (PMID 41334873, 2025). "We could show that TAK1 determines whether acinar cells will survive, transdifferentiate into ductal cells and subsequently develop into cancer cells or will succumb to PCD through RIPK1-dependent necroptosis and apoptosis." (PMID 39971907, 2025). "The development of cancer has been the subject of extensive research, with a total of 615 papers examining the effects of RIPK1, 119 papers investigating the effects of RIPK2, 550 papers exploring the effects of RIPK3, and 54 papers analyzing the effects of RIPK4." (PMID 38164277, 2024). "Besides, previous studies have shown that TNFSF10 can induce autophagy through the MAPK8 activation pathway of TRAF2 and RIPK1, which in turn blunts the apoptosis of cancer cells." (PMID 38375157, 2024).